PSMB1 (proteasome 20S subunit beta 1)
Description:
Non-catalytic component of the 20S core proteasome complex involved in the proteolytic degradation of most intracellular proteins. This complex plays numerous essential roles within the cell by associating with different regulatory particles. Associated with two 19S regulatory particles, forms the 26S proteasome and thus participates in the ATP-dependent degradation of ubiquitinated proteins. The 26S proteasome plays a key role in the maintenance of protein homeostasis by removing misfolded or damaged proteins that could impair cellular functions, and by removing proteins whose functions are no longer required. Associated with the PA200 or PA28, the 20S proteasome mediates ubiquitin-independent protein degradation. This type of proteolysis is required in several pathways including spermatogenesis (20S-PA200 complex) or generation of a subset of MHC class I-presented antigenic peptides (20S-PA28 complex).
Synonyms: PSC5; PMSB1; HC5; NEDMHAL
Tractability: Small molecule: an approved drug acts on it; a structure with a bound ligand is known; a high-quality ligand is known; it belongs to a druggable protein family. Antibody: its Gene Ontology location is reachable by antibodies, with high confidence. PROTAC: ubiquitination databases record sites on it; its protein half-life has been measured; a small molecule that binds it is known.
Target class: Threonine protease; Protease; Threonine protease T1A subfamily; Threonine protease PBT clan; Enzyme
Gene: Protein-coding gene on chromosome 6 (170,535,116 to 170,553,327, reverse strand). Ensembl gene ENSG00000008018.
Subcellular location: Cytoplasm; Nucleus
Subcellular location (Human Protein Atlas): Nucleoplasm
Pathways (Reactome):
Immune System: AMPK-induced ERAD and lysosome mediated degradation of PD-L1(CD274); Activation of NF-kappaB in B cells; Antigen processing: Ub, ATP-independent proteasomal degradation; Antigen processing: Ubiquitination & Proteasome degradation; CLEC7A (Dectin-1) signaling; Cross-presentation of soluble exogenous antigens (endosomes); Dectin-1 mediated noncanonical NF-kB signaling; Downstream TCR signaling; ER-Phagosome pathway; FCERI mediated NF-kB activation; GSK3B-mediated proteasomal degradation of PD-L1(CD274); Interleukin-1 signaling; NIK-->noncanonical NF-kB signaling; Neutrophil degranulation; SPOP-mediated proteasomal degradation of PD-L1(CD274); TNFR2 non-canonical NF-kB pathway
Cell Cycle: APC/C:Cdc20 mediated degradation of Securin; APC/C:Cdh1 mediated degradation of Cdc20 and other APC/C:Cdh1 targeted proteins in late mitosis/early G1; Autodegradation of Cdh1 by Cdh1:APC/C; Autodegradation of the E3 ubiquitin ligase COP1; Cdc20:Phospho-APC/C mediated degradation of Cyclin A; FBXL7 down-regulates AURKA during mitotic entry and in early mitosis; G2/M Checkpoints; SCF(Skp2)-mediated degradation of p27/p21; SCF-beta-TrCP mediated degradation of Emi1; Separation of Sister Chromatids; The role of GTSE1 in G2/M progression after G2 checkpoint; Ubiquitin-Mediated Degradation of Phosphorylated Cdc25A; Ubiquitin-dependent degradation of Cyclin D
Signal Transduction: Asymmetric localization of PCP proteins; Degradation of AXIN; Degradation of DVL; Degradation of GLI1 by the proteasome; Degradation of GLI2 by the proteasome; Degradation of beta-catenin by the destruction complex; GLI3 is processed to GLI3R by the proteasome; Hedgehog 'on' state; Hedgehog ligand biogenesis; MAPK6/MAPK4 signaling; Negative regulation of NOTCH4 signaling
and 29 more pathways
Gene Ontology:
Molecular function: protein binding; structural constituent of proteasome
Biological process: proteasomal protein catabolic process; proteasome-mediated ubiquitin-dependent protein catabolic process; regulation of proteasomal protein catabolic process; response to oxidative stress; apoptotic process; CD8-positive, alpha-beta T cell differentiation; CD8-positive, alpha-beta T cell homeostasis; cellular response to type I interferon; DNA damage response; DNA repair; flagellated sperm motility; immune system process; meiotic cell cycle; negative regulation of regulatory T cell differentiation; positive regulation of interleukin-2 production; positive regulation of tumor necrosis factor production; positive regulation of type II interferon production; proteasomal ubiquitin-independent protein catabolic process; regulation of G1/S transition of mitotic cell cycle; response to type II interferon; spermatogenesis; T-helper 1 cell differentiation; T-helper 17 cell differentiation; thymic T cell selection; protein catabolic process
Cellular component: cytoplasm; extracellular exosome; nucleoplasm; nucleus; proteasome complex; proteasome core complex; cytosol; extracellular region; ficolin-1-rich granule lumen; proteasome core complex, beta-subunit complex; proteasome storage granule; secretory granule lumen; spermatoproteasome complex; synaptic vesicle
Genetic constraint (gnomAD): Loss-of-function variants: 5 observed, 19.14 expected, observed/expected ratio (o/e) 0.26, 90% interval 0.14 to 0.55. The upper end of that interval is the gene's LOEUF score, 0.55, which puts it in group 2 of 6, group 1 being the genes least tolerant of losing a copy. Missense variants: 268 observed, 300.83 expected, observed/expected ratio (o/e) 0.89, 90% interval 0.81 to 0.99. Synonymous variants: 113 observed, 116.8 expected, observed/expected ratio (o/e) 0.97, 90% interval 0.83 to 1.13.
Homologues: Orthologues: chimpanzee PSMB1 (100% identical), macaque PSMB1 (98% identical), pig PSMB1 (95% identical), dog PSMB1 (94% identical), mouse Psmb1 (93% identical), guinea pig PSMB1 (91% identical), rabbit PSMB1 (87% identical), zebrafish psmb1 (80% identical), tropical clawed frog psmb1 (78% identical), rat Psmb1 (61% identical), Drosophila melanogaster Prosbeta6 (48% identical), Caenorhabditis elegans pbs-6 (40% identical). Paralogues in human: PSMB9 (22% identical), PSMB11 (21% identical), PSMB10 (21% identical), PSMB8 (21% identical), PSMB3 (20% identical), PSMB5 (20% identical), PSMB2 (20% identical), PSMB7 (20% identical), PSMB6 (19% identical), PSMB4 (17% identical), PSMA4 (17% identical), PSMA5 (16% identical), and 6 more.